PNPLA3 (patatin like domain 3, 1-acylglycerol-3-phosphate O-acyltransferase )
Diseases named in the same sentence as PNPLA3 in open-access papers (continued):
Sharing a sentence is not in itself a finding about the gene and the disease.
Cirrhosis (continued). "Patatin-like phospholipase structural domain 3 (PNPLA3) is the major susceptibility gene for NAFLD, and its PNPLA3 I148M (rs738409, C > G) is strongly associated not only with hepatic fat content but also with the progression of NAFLD to NASH, fibrosis, and cirrhosis." (PMID 36825197, 2023). "In detail, variants rs738409 in PNPLA3, rs641738 in MBOAT7, and rs58542926 in TM6SF2 are associated with increased triglyceride production, accumulation of very low-density lipoprotein (VLDL) and triglycerides and increased risk of developing cirrhosis, respectively." (PMID 36835291, 2023). "Since BMI was independently associated with hepatic fibrosis and cirrhosis in these analyses, we therefore also stratified CHC patients according to BMI status into obese (BMI ≥ 25) and non-obese (BMI < 25) sub-groups and analyzed for any potential genetic associations of PNPLA3 and TM6SF2 variants." (PMID 36028802, 2022). "Notably, TM6SF2 rs58542926 combined with PNPLA3 rs738409 may have additive value in predicting ALD cirrhosis progression; additionally, both of them had a potential risk for HCC development in ALD patients." (PMID 34068269, 2021). "TGF-β1 (Arg25Pro) GG variant may be associated with HCC risk in HCV-related liver cirrhosis patients, while PNPLA3 (I148M) GG variant may be associated with cirrhosis development but not HCC risk in HCV-related liver cirrhosis patients." (PMID 34711009, 2021). "The PNPLA3 GG genotype seems to have an approximately twofold higher risk of developing hepatic steatosis, a three- to four-fold higher risk of developing NASH and cirrhosis, and an up to 12-fold higher risk of developing HCC as compared with the PNPL3 CC genotype." (PMID 32570776, 2020). "In addition to PNPLA3 genotype, the cohort of liver samples was divided and analyzed according to fibrosis stage, ranging from F = 1 and 2 for ‘mild’/periportal to F = 3 and 4 for ‘severe’ hepatic fibrosis/cirrhosis." (PMID 32043752, 2020). "The results of our study showed that direction for TM6SF2 rs58542926 between fibrosis and cirrhosis groups was different, but the significance level was not reached and this genetic variant alone or combined with PNPLA3 risk genotype was not linked with liver fibrosis or cirrhosis." (PMID 30875804, 2019). "Besides PNPLA3, other genetic factors are involved in cirrhosis or fibrosis progression." (PMID 26950933, 2016). "Multivariate analysis showed that older age (OR = 1.06; 95% CI: 1.03–1.09; p = 0.0001), higher BMI (OR = 1.11; 95% CI: 1.00–1.24; p = 0.0576), and PNPLA3 genotype GG (OR = 2.07; 95% CI: 0.94–4.55; p = 0.0712) were factors independently associated with progression to cirrhosis (data not shown)." (PMID 25713769, 2015). "PNPLA3 148M predisposes to fibrosis progression, but whether the effect on carcinogenesis is independent of cirrhosis is still debated." (PMID 24155878, 2013). "Importantly, the effect attributable to the PNPLA3 p.I138M polymorphism in nutritional cirrhosis was not correlated to age, gender, body mass index or diabetes in line with previous reports." (PMID 22087248, 2011). "Another study reported that the combination of PNPLA3, TM6SF2 and HSD17B13 predicted NASH-cirrhosis and HCC in general population settings." (PMID 36266438, 2022). "Despite the substantial genetic evidence implicating rs738409 and PNPLA3 with cirrhosis and HCC of different aetiologies, the function of the PNPLA3 protein remains uncertain as does the effect of the Ile148Met substitution." (PMID 27888630, 2016). "We genotyped SNPs in EGF, PNPLA3, and IL28B from liver tissue from 169 patients with biopsy-proven HCV cirrhosis." (PMID 25504078, 2014). "Genotypic distributions for PNPLA3 and TM6SF2 polymorphisms conformed to Hardy–Weinberg equilibrium and did not associate with fibrosis grades ≥ F2 or cirrhosis in any of the genetic models tested (all p = > 0.05)." (PMID 36028802, 2022).
Cirrhosis (continued). "Nevertheless, in the present CHC patients of Pakistani origin we did not detect any significant effect of PNPLA3 and TM6SF2 variants in modulating serum markers of hepatic injury nor hepatic fibrosis and cirrhosis." (PMID 36028802, 2022). "By univariate analysis, the SNPs in PNPLA3, TM6SF2 and PDCD1 rs7421861 were significantly different in NAFLD-HCC versus controls, but none retained significance after regression analysis including age, sex and cirrhosis." (PMID 33808740, 2021). "In this study, we confirmed that the PNPLA3 genotype I148M was associated with the development of HCC in Japanese patients with CHC, and is one of risk factors for cirrhosis in the patients without past history of IFN treatment." (PMID 25713769, 2015). "PNPLA3 genotype I148M is one of risk factors for developing HCC in Japanese CHC patients, and is one of risk factors for progress to cirrhosis in the patients without past history of interferon treatment." (PMID 25713769, 2015). "In contrast to some previous investigations, we found that the effects of cardiometabolic and lifestyle risk factors were largely independent of genetic predisposition as assessed by the PNPLA3 genetic variant, the PRS-MASLD, the PRS-cirrhosis, and the PRS-cALT." (PMID 39049959, 2024). "Since the rs738409 PNPLA3 and rs72613567 HSD17B13 but not the rs58542926 TM6SF2 were significantly associated with the development of liver cirrhosis over time, we delineated a predictive model for cirrhosis development over time." (PMID 37626629, 2023). "PNPLA3 and TM6SF2 variants do not appear to modulate development of hepatic fibrosis or cirrhosis in present CHC patients of Pakistani origin, and may be of more relevance in liver pathology involving abnormalities in hepatic fat accumulation." (PMID 36028802, 2022). "Similarly, increasing number of risk alleles of PNPLA3 and TM6SF2 polymorphisms had no trend effect on serum liver enzyme activities or proportion of CHC patients with significant or advanced fibrosis or cirrhosis (p = > 0.05)." (PMID 36028802, 2022). "Also, no significant impact of PNPLA3 and TM6SF2 variants on hepatic fibrosis and cirrhosis of CHC background was highlighted in some of such studies from other populations." (PMID 36028802, 2022). "The germline genetic testing was limited to the 226 cancer-predisposition genes included in the CZECANCA panel, which was designed for the analysis of cancer predisposition but does not cover some of the known cirrhosis-predisposing genes (i.e., APOB, HFE, PNPLA3, SERPINA1)." (PMID 36612198, 2022). "Viewing the groups with the non cancer cases also broken down into those with and without cirrhosis confirmed that the most striking associations of both the PNPLA3 and the TM6SF2 variants were with the presence of cirrhosis, rather than with the presence of cancer." (PMID 33808740, 2021). "Finally, we did not detect a sex-specific impact of the PNPLA3 (female patients P = 0.57, male patients P = 0.84) or TM6SF2 polymorphisms (female patients P = 0.91, male patients P = 0.72) on the frequency of cirrhosis." (PMID 30161167, 2018). "However, no study has evaluated the influence of IL28B, EGF, and PNPLA3 genotypes on the natural history of HCV-related cirrhosis or examined these SNPs in the same population." (PMID 25504078, 2014). "We compared distributions of PNPLA3 genotypes in 80 and 81 Caucasian patients with alcoholic and hepatitis C virus (HCV)-associated HCC to 80 and 81 age- and sex-matched patients with alcohol-related and HCV-related cirrhosis without HCC, respectively." (PMID 22087248, 2011). "The landmark PNPLA3 study measured hepatic fat content by 1H-MRS and examined inflammation through serum levels of ALT to suggest that rs738409 could increase risk of NASH, but the study itself did not focus on histologic NASH or cirrhosis." (PMID 34950105, 2021).
liver fibrosis (125 papers, 2010 to 2026). "Consecutively, we studied prespecified factors known to be associated with liver fibrosis next to PNPLA3 and TM6SF2 risk alleles." (PMID 41492318, 2026). "Next, we explored the potential impact of the risk of advanced liver fibrosis and carriage of PNPLA3‐I148M on the risk of prevalent CKD in participants with SLD (HSI > 36)." (PMID 39548715, 2025). "In one Asian prospective study, visceral fat accumulation was significantly associated with significant liver fibrosis only among PNPLA3 rs738409 C > G carriers (aOR 1.05 for GG homozygosity; aOR 1.03 for CG heterozygosity)." (PMID 39412170, 2025). "Associations between SLD, MetS, risk of advanced liver fibrosis, and PNPLA3‐I148M with prevalent CKD." (PMID 39548715, 2025). "In this study, the PNPLA3 rs738409 GG genotype was associated with worse liver fat mass, liver fibrosis, and insulin resistance than the other genotypes." (PMID 40074353, 2025). "This study investigated the role of the stress-response co-chaperone BAG3 as a circulating biomarker of hepatic fibrosis and its association with PNPLA3 and TM6SF2 genotypes." (PMID 41373448, 2025). "A phase 2b study for histological assessments has been initiated, and it aims to evaluate the treatment effects of the hepatic silencing of PNPLA3 on histological MASH and liver fibrosis in patients with the PNPLA3 148M risk allele variant." (PMID 40507973, 2025). "The selected instrumental variables notably diminished the risk of NAFLD and liver fibrosis, indicating that these variables accurately represent the effects of PNPLA3 inhibition." (PMID 40881642, 2025). "With regard to omega FAs and their interaction with gene variants, arachidonic acid (n-6 PUFA) intake has been shown to be associated with increased liver fibrosis in carriers of the PNPLA3 I148M variant." (PMID 38247511, 2024). "In contrast, a systematic review and meta-analysis determining the association between PNPLA3 rs738409 SNP and liver fibrosis severity, HCC risk and prognosis among patients with liver disease reported increased risk of advanced fibrosis." (PMID 39201329, 2024). "The potency of anti-PNPLA3 ASO-GalNAc in improving NAFLD conditions caused by mutated PNPLA3, including liver fibrosis, was proven." (PMID 38665220, 2024). "Logistic regression analysis for the association of PNPLA3 rs738409 C>G with different severities of liver fibrosis in MASLD was assessed." (PMID 38674389, 2024). "In patients already diagnosed with NAFLD, however, PNPLA3 confers a greater risk for hepatic fibrosis progression than lower muscle mass." (PMID 36403577, 2023). "PNPLA3-I148M has also been reported to cause liver fibrosis by reducing its retinyl-palmitate hydrolytic activity, promoting intercellular matrix metalloproteinase expression and fibrotic remodeling in HSCs." (PMID 37298640, 2023). "In the current study, we have determined that participants with PNPLA3 risk variants are more susceptible to developing NAFLD‐related hepatic fibrosis, after adjusting for confounders including muscle mass." (PMID 36403577, 2023). "The study reported a strong association between IR and patatin-like phospholipase domain-containing protein 3 (PNPLA3) in the progression of hepatic fibrosis." (PMID 37108615, 2023). "The main PHH donor used in the model is heterozygous for the PNPLA3 I148M mutation, predisposing for liver fibrosis development." (PMID 36672237, 2023). "In carriers of this allele, the effects of the PNPLA3 rs738409 GG genotype on advanced hepatic fibrosis are attenuated." (PMID 37644826, 2023). "Two machine learning algorithms confirmed separately the importance of rs738409 (PNPLA3) in predicting risk of advanced liver fibrosis." (PMID 36386790, 2022). "Our results also show an independent association between CG/GG in PNPLA3 and the presence of steatohepatitis and liver fibrosis in this population." (PMID 36110512, 2022).
liver fibrosis (continued). "The PNPLA3 G allele variant was associated with steatohepatitis [OR 4.9 (1.3–18); p 0.02] and liver fibrosis [OR 4.3 (1.1–17.4); p 0.04], and the MBOAT7-TMC4 A allele variant was associated with steatohepatitis [OR 6.6 (1.6–27.6); p 0.01]." (PMID 36110512, 2022). "The presence of the G allele of SNP rs738409 in PNPLA3 gene was also associated with significant liver fibrosis (p = 0.0184)." (PMID 35630668, 2022). "We observed that harboring the PNPLA3 G variant and aspartate aminotransferase levels were independently associated with liver fibrosis (any grade)." (PMID 36110512, 2022). "A study investigating the association between genetic risk and liver fibrosis by MRE demonstrated that the PNPLA3 risk variant is associated with an increase in liver fibrosis." (PMID 36317632, 2022). "Further studies are needed in order to validate and confirm our results, but it seems that IR mediates the risk of progression towards advanced liver fibrosis induced by PNPLA3 rs738409 and TM6SF2 rs58542926 polymorphisms." (PMID 35625751, 2022). "The proportion of NAFLD patients with liver fibrosis was relevant in the present admixed T2D population, and was associated with PNPLA3 polymorphisms." (PMID 35630668, 2022). "Several variants had stronger associations than the well-known PNPLA3 variant and a panel of four variants was strongly associated with risk for advanced liver fibrosis." (PMID 36386790, 2022). "PNPLA3 was also associated with prevalence, pathological severity—including that of liver fibrosis—hepatocarcinogenesis, and mortality in NAFLD patients." (PMID 35886046, 2022). "We previously reported that carriage of the HSD17B13 rs6834314 G allele attenuated the effect of the PNPLA3 rs738409 GG genotype on advanced hepatic fibrosis in Japanese patients with NAFLD19." (PMID 36266438, 2022). "Several studies have shown an association between liver fibrosis and PNPLA3 expression in HSC cells and activated HSCs carrying the I148M variant of the PNPLA3 gene have been found to exhibit enhanced pro-inflammatory and pro-fibrogenic properties." (PMID 36471376, 2022). "We also demonstrate that the common missense variant of MTARC1 p.A165T is protective against hepatic fibrosis in obese individuals and ameliorates the harmful effects of the PNPLA3 p.I148M minor allele." (PMID 36555467, 2022). "Nevertheless, previous studies on the allelic variants of PNPLA3 demonstrate their association with the different stages of liver fibrosis." (PMID 36110512, 2022). "In conclusion, in this evaluation of an admixed T2D population, we found that NAFLD with liver fibrosis by TE was relevant and associated with SNP rs738409 in PNPLA3." (PMID 35630668, 2022). "Intakes of several dietary types of unsaturated fat have different associations with liver fibrosis by PNPLA3 genotype after accounting for sex, caloric intake, and liver fat." (PMID 34065978, 2021). "We previously reported that carriage of the HSD17B13 G allele attenuated the effect of the PNPLA3 GG genotype in advanced liver fibrosis." (PMID 33922278, 2021). "The PNPLA3 rs738409 C > G variant is associated with the severity of liver fibrosis and fibrosis progression in patients with NAFLD." (PMID 34503201, 2021). "The I148M variant of the PNPLA3 gene represents a higher risk of severe liver fibrosis, and PNPLA3 I148M up-regulates Hedgehog and YAP Signaling in human HSCs." (PMID 34440218, 2021). "The mechanism underlying the effects of PNPLA3 on hepatic fibrosis and hepatocarcinogenesis is still unclear." (PMID 33922278, 2021). "Because of individual genetic variants PNPLA3 was the only one with significant association to liver fibrosis in univariate analysis, so we also measured performance of the model using only this variant instead of GRS." (PMID 33429859, 2021). "We recently reported that carriage of the HSD17B13 rs6834314 G allele attenuated the effect of the PNPLA3 rs738409 GG genotype on advanced hepatic fibrosis." (PMID 33922278, 2021).
liver fibrosis (continued). "The I148M variant of the PNPLA3 gene represents a risk factor for development of severe liver fibrosis." (PMID 33218077, 2020). "In conclusion, these observations emphasize that PNPLA3 expression in human biopsies is closely linked with HSCs activation and liver fibrosis progression in NASH livers, being metabolically controlled by glucose and pro‐steatotic conditions." (PMID 32043752, 2020). "Specifically looking to HCV infection, PNPLA3 I148M variant has been related to an increased risk of liver fibrosis progression." (PMID 32382265, 2020). "In Japan, we previously reported that severe hepatic fibrosis (F3/4) and PNPLA3 GG are significant factors associated with incident HCC development in Japanese patients with biopsy proven NAFLD." (PMID 32570776, 2020). "The effects of PNPLA3 have been well established in previous research, but we wanted to see if the risk of liver fibrosis is changed by a certain combination of PNPLA3 and TM6SF2 or MBOAT7 genotypes." (PMID 30875804, 2019). "In that study, the authors demonstrated that PNPLA3 is highly expressed in human hepatic stellate cells (HSCs) suggesting a potential link between HSCs, retinoid metabolism, and PNPLA3 in determining the susceptibility to hepatic fibrosis." (PMID 29258449, 2017). "Lastly, this study did not support the previous report which indicated the linkage between the PNPLA3 rs738409 genetic polymorphism and advanced hepatic fibrosis in patients with NAFLD." (PMID 26485523, 2015). "Our study provides novel data on the impact of a PNPLA3 risk allele on liver fibrosis progression in HIV/HCV coinfection." (PMID 26599080, 2015). "The PNPLA3 I148M sequence variant favors hepatic lipid accumulation and confers susceptibility to hepatic fibrosis and hepatocellular carcinoma." (PMID 25171251, 2014). "In patients with chronic hepatitis C, the PNPLA3 rs738409 polymorphism was strongly associated with advanced hepatic fibrosis." (PMID 25337145, 2014). "The importance of our study resides in establishing a new role for PNPLA3 in retinoid metabolism in HSCs with possible important implications for liver fibrosis and hepatocellular carcinoma susceptibility." (PMID 24670599, 2014). "Conversely, this enzymatic activity is markedly reduced with purified PNPLA3 148M, a common mutation robustly associated with liver fibrosis and hepatocellular carcinoma development." (PMID 24670599, 2014). "The common PNPLA3 (adiponutrin) variant, p.I148M, was identified as a genetic determinant of liver fibrosis." (PMID 24152445, 2013). "Liver fibrosis is marked by increased oxidative stress and patients carrying the PNPLA3 I148M variant demonstrated an increase in systemic oxidative stress as quantified in serum levels of soluble NOX2‐derived peptide (sNOX2‐dp) and 8‐isoprostaglandin F2α (8‐iso‐PGF2α)." (PMID 39394864, 2025). "Moreover, PNPLA3 rs738409 facilitates liver fibrosis progression due to the loss of retinyl palmitate lipase activity and impaired retinol production." (PMID 39713746, 2024). "Cox proportional hazard models for incident NAFLD or hepatic fibrosis incorporating age, sex, BMI of ≥25 kg/m2, metabolic syndrome and PNPLA3 and TM6SF2 risk alleles were used to assess the independent determinants for incident NAFLD and hepatic fibrosis among individuals with NAFLD at baseline." (PMID 36403577, 2023). "Our results demonstrated for the first time that PNPLA3-I148M causes mitochondrial dysfunction of LX-2 cells through the accumulation of free cholesterol, thereby promoting the activation of LX-2 cells and the development of liver fibrosis." (PMID 37298640, 2023). "Additionally, the presence of the PNPLA3 polymorphism, a gene associated with liver fibrosis severity in NAFLD patients, is more frequent in the Hispanic population." (PMID 37892625, 2023).